BRAF (B-Raf proto-oncogene, serine/threonine kinase)
Diseases named in the same sentence as BRAF in open-access papers (continued):
Sharing a sentence is not in itself a finding about the gene and the disease.
tumor (continued). "The loss of ECAD was associated with higher tumor budding and positivity for the BRAF mutation-specific antibody (all p < 0.05)." (PMID 33256003, 2020). "For the identification of LS through screening all CRCs for MMR deficiency, the inclusion of BRAF c.1799 avoids expenditure on additional tests as a single tumor assay is required before germline testing." (PMID 31471937, 2020). "Large-scale tumor profiling studies using NGS have revealed significant genomic similarities, with shared actionable alterations in driver genes, among different tumor types (e.g., BRAF mutations are found across multiple tumor types)." (PMID 31937368, 2020). "RNF43-mutant tumours were significantly enriched for right colonic distribution, BRAF mutations, microsatellite instability and CMS1 (MSI immune) classification, consistent with predominantly sessile serrated lesion aetiology." (PMID 31563876, 2020). "By multivariate analysis, group A tumors are characterized by tall cell histotype, BRAF V600E mutation, tumor fibrosis, aggressive growth with invasive features, vascular invasion, lymph node metastases, and intermediate ATA risk." (PMID 31963890, 2020). "The detection of BRAF mutations is commonly performed on DNA extracted from tumor tissue samples, using a molecular approach." (PMID 32751423, 2020). "SNVs present with allele frequency of ≤ 5% (rare SNVs) occur frequently in genes commonly mutated during cancer (for example, EGFR, KRAS, PIK3CA, and BRAF), and can provide insight into the dynamics of subclonal tumour populations." (PMID 32024475, 2020). "Only one of these five cases (MIA_10) had a detectable splicing variant (BRAF p61) in plasma which was concordant with the results of the matched tumour sample." (PMID 33216826, 2020). "Both APC and BRAF mutations are tumor-initiating events and give rise to different precursor lesions." (PMID 32384699, 2020). "It is generally believed that patients with any RAS/BRAF mutations in either tumor tissue or plasma have less treatment benefit than patients who have no mutations." (PMID 33066758, 2020). "All the 8 BRAF mutations disclosed by SS/Real Time PCR assay/TherascreenTM BRAF Pyro Kit were called in all tumor samples with a coverage >200x and an VAF > 18.8%." (PMID 33317587, 2020). "In patients with double (KRAS and BRAF) wild-type tumor, median OS was 10 months if CDX2 loss (n = 10) compared to 27 months if CDX2 expressed (n = 77) (p = 0.576)." (PMID 32117703, 2020). "One patient (7.5%) with identified BRAF mutation showed tumor recurrence during the course of the disease (p > 0.05)." (PMID 31919458, 2020). "We determined the tumor’s proto-oncogene B-Raf (BRAF) and NRAS mutational status using Sanger sequencing." (PMID 32028967, 2020). "The BRAF-mutated tumor was more often related with pathologic characteristics such as a location on the right-side, lymph-node metastases, mucin component, tumor thrombus, perineural invasion, and low differentiation grade." (PMID 32161617, 2020). "The aim of this study was to determine the prevalence, prognostic, and predictive effect of CDX2 loss in unselected patients of mCRC in relation to tumor differentiation, BRAF, KRAS, and MSI status." (PMID 32117703, 2020). "Differences in the geographical region or tumor stage should be considered when interpreting the impact of a BRAF mutation on recurrence." (PMID 32722429, 2020). "BRAF or NRAS mutations previously identified in tumour tissues were found in 34 out of 68 patients, representing an overall 50% sensitivity between tissue analyses and circulating DNA analysis on the Cobas system." (PMID 32664549, 2020). "Additional molecular analyses found BRAF V600E mutations in both resections, supporting the idea that the recurrent tumor had derived from PXA." (PMID 31941461, 2020).
tumor (continued). "It is well known that the presence of KRAS and BRAF mutations in a patient’s tumor correlates strongly with resistance to anti-EGFR antibodies, and therefore, all patients are tested for BRAF and KRAS mutations before initiating anti-EGFR therapy." (PMID 32290033, 2020). "Long term proliferation assays also confirmed that combination therapy using BET inhibitor along with either BRAF or ERK signaling efficiently prevented growth of tumor cells carrying mutation of FBXW7." (PMID 32907612, 2020). "When activated in tumor cells, the BRAF/MEK/ERK pathway is commonly associated with cell proliferation and survival." (PMID 33268358, 2020). "Nearly 60% of melanoma patients’ tumors harbor mutations in the BRAF gene that correlate with aggressive tumor phenotypes and poor prognosis." (PMID 32978468, 2020). "The QUASAR trial, which evaluated BRAF mutational status as predictive markers for 5‐FU/LV chemotherapy, was unable to detect an association between BRAF mutational status and tumor response to 5‐FU/LV chemotherapy." (PMID 33319153, 2020). "In view of the additional ERBB2 mutation, which affects the RAS/RAF/MEK/ERK pathway 30, the tumor board recommended an off-label therapy with combined BRAF- and MEK-inhibition together with the intrathecal application of methotrexate." (PMID 31903155, 2020). "Our results strongly support a central role for the miR-146a/COX2 axis in modulating key components of tumor growth and survival associated with the onset of BRAF/MEKi resistance." (PMID 32967672, 2020). "In subgroup analysis, both geographical region (HRs for America, Asia, and Europe were 2.16, 1.31 and 0.66, respectively) and tumor stage (HRs for stage I and II were 1.51 and 4.45, respectively) can affect the HRs of the BRAF mutation for recurrence." (PMID 32722429, 2020). "Other factors known to influence prognosis include histological differentiation grade, tumour sidedness and BRAF mutations." (PMID 32647253, 2020). "In our study, the case where both KRAS and BRAF mutations are identified is a 75-year-old female with a 3 cm tumor in rectum." (PMID 32582557, 2020). "Further oncogenic lesions such as CDKN2A p16INK4A loss are required in order to reactivate proliferation, indicating that BRAF V600E mutations require PI3K/Akt dysregulation for the tumor to progress." (PMID 33348922, 2020). "Different from MEK inhibitors, which can inhibit both tumor cells and normal cells at the same time, vemurafenib inhibits only tumor cells with the BRAF V600E mutation." (PMID 32476297, 2020). "Acquired resistance is a cellular alteration in addition to the BRAFV600E mutation that facilitates tumour cells to grow despite BRAF inhibitor (BRAFi) therapy." (PMID 32411231, 2020). "BRAF p61 was also detectable in plasma of one of four patients with confirmed BRAF splicing variants in their progressing tumours." (PMID 33216826, 2020). "Another two patients (P33 and P34) were identified as carrying a BRAF mutation in paired primary tumors and tumor-derived organoids." (PMID 32290033, 2020). "Simultaneously, it should be emphasized that the Idylla BRAF mutation assay has previously been shown to be able to accurately detect BRAF mutational status in FFPE samples with even 2% tumor cell content." (PMID 32879641, 2020). "To date, it has been shown that KRAS and BRAF mutations increase the glycolytic capacity of tumor cells and their glutaminolysis." (PMID 32231083, 2020). "BRAF V600 mutations are identified mostly in CM but should also be considered in the treatment algorithm of MM and even in atypical tumor localizations, such as PMMB." (PMID 32825562, 2020). "In bone marrow tumor DNA samples, the detection rate of BRAF V600Mx mutations was 4/83 (5%), KRAS Mx was 13/83 (16%), NRAS G12/G13 was 3/83 (4%) and NRAS Q61 was 14/83 (17%), which were approximately equivalent to those found using an NGS method." (PMID 32284750, 2020).
tumor (continued). "In contrast, patients with LEATs demonstrating astrocytic differentiation, BRAF mutation as well as activation of MAPK/FGFR/EGFR oncogene pathways are at higher risk of tumor recurrence and malignant progression." (PMID 31919458, 2020). "Of note, TERT mRNA expression levels were not different when considering other genetic alterations present in the tumours, such as BRAF, NRAS mutations and RET/PTC or PAX8/PPARγ rearrangements (Figure A1)." (PMID 32659948, 2020). "Accordingly, BRAF mutated tumours (34%) and tumours, classified as MSI (24%) and CMS1 (37%), were also slightly over-represented." (PMID 33228141, 2020). "In cPTCs, higher TUBB3 expression was correlated with stromal TUBB3 expression, higher tumor budding, and positivity for BRAF mutation-specific antibody (all p < 0.05)." (PMID 33256003, 2020). "Among the 20 cases, 19 cases had normal BRAF sequence and only one tumour (Case number A7) had BRAF V600E mutational sequence." (PMID 32328381, 2020). "Half a year later, in July 2019, after confirming that the tumour still harboured a BRAF p.V600E mutation, combined treatment with BRAF and MEK inhibitors was reintroduced, due to progressive disease with multiple lung metastases." (PMID 33043759, 2020). "CDX2-negative tumours are often associated with several adverse prognostic variables (e.g., advanced stage, poor differentiation, vascular invasion, BRAF mutation and CIMP-positive status) and lower DFS." (PMID 33209121, 2020). "Differences in geographical region or tumor stage should be considered to interpret the effect of BRAF mutations on the risk of recurrence." (PMID 32722429, 2020). "By contrast, the serrated neoplasia pathway is initiated by activating mutations in BRAF and often progresses to malignancy via MLH1 hypermethylation, microsatellite instability and a plethora of epigenetic alterations." (PMID 32384699, 2020). "Higher IL1RN expression was significantly associated with shorter progression-free survival (PFS), advanced tumor stage, tumor metastasis, increased incidence of BRAF mutations, and decreased incidence of N-RAS and H-RAS mutations." (PMID 33238942, 2020). "A BRAF mutation analysis is mandatory, but a wider evaluation of tumor mutational status (e.g. by next-generation sequencing) is desirable." (PMID 33292371, 2020). "Patients diagnosed with tumor BRAF mutation undergo targeted therapy with a BRAF inhibitors (vemurafenib or dabrafenib) in the first line of treatment." (PMID 32992737, 2020). "A second type of cellular senescence serves as a major tumor suppressor mechanism and results from oncogenic stress due to activating mutations in oncogenes (e.g. BRAF) or inactivating mutations in tumor suppressor genes (e.g. PTEN)." (PMID 32029712, 2020). "Preclinical studies suggest that ERK inhibitors have an advantage over inhibiting the growth of BRAF/RAS mutated tumor and overcoming BRAF or/and MEK inhibitor resistance." (PMID 33287111, 2020). "Davies and coworkers first described a BRAF V600E mutation in 2002 in several tumor entities, especially in malignant melanomas." (PMID 32151273, 2020). "BRAF V600E mutations significantly related to tumor location, degree of differentiation, and histopathology (p < .01)." (PMID 33145020, 2020). "In preclinical models and in retrospective analyses of patients undergoing BRAF inhibitor therapy, blockade of this pathway was linked to a more favorable microenvironment function, with an increased number of activated tumor‐infiltrating lymphocytes." (PMID 32330348, 2020). "Although all BRAF mutations were poorly differentiated, a significant association also emerged between BRAF V600E mutations and tumor histopathology (p < .01)." (PMID 33145020, 2020). "It is noteworthy that all four deceased patients from the local database died because of tumor recurrence and carried BRAF mutations." (PMID 31919458, 2020).
tumor (continued). "In the subgroup of patients with tumour BRAF mutation, it would be of interest to compare continuous induction chemotherapy with capecitabine plus bevacizumab chemotherapy or encorafenib plus cetuximab." (PMID 32015513, 2020). "We also detected a significant association between BRAF V600E mutations and degree of tumor differentiation (p < .05)." (PMID 33145020, 2020). "The BRAF V600E mutation in both primary tumor and LNM negatively correlated with the size of the largest metastatic focus of LNM (Odds ratio, OR = 0.297, 95% CI 0.143–0.616, P = 0.001; OR = 0.242, 95% CI 0.119–0.492, P = 0.000, respectively)." (PMID 33064665, 2020). "In a prospective study of 106 patient samples of CRC, ctDNA analysis of KRAS and BRAF mutational status was compared to the analysis of tumor tissue." (PMID 32010431, 2020). "In this study, the BRAF V600E mutation was evaluated in both the primary tumor and LNM in PTC patients." (PMID 33064665, 2020). "The EGFR-targeting antibody cetuximab is also used under the prerequisite of wildtype KRAS or BRAF status, as mutations in these oncogenes render tumours insensitive to EGFR-targeted therapy." (PMID 32647253, 2020). "Short nucleic fragments, carrying genetic information including BRAF V600 mutations, are released by tumours allowing for blood based monitoring." (PMID 33139839, 2020). "MSI status, KRAS, and BRAF mutation status were also characterized and compared between primary tumor tissues and tumor-derived organoids from 15 patients." (PMID 32290033, 2020). "Oncogenic BRAF mutations are associated with immune escape of tumor cells and a lower presence of TILs." (PMID 32188503, 2020). "Activating mutations of KRAS codon 12 were detected in four patients, and oncogenic mutations of NRAS (G13V) and BRAF (V600E) were each identified in one additional tumor, contributing to a prevalence of 54.4% for activating mutations of RAS pathway." (PMID 31953485, 2020). "BRAF alternations frequently appeared in this subgroup and were associated with poor oncological outcome and tumor recurrence in almost half of the patients." (PMID 31919458, 2020). "Large-scale tumor sequencing and subsequent functional analysis of individual mutations have revealed that a few mutations possess reduced BRAF kinase activity." (PMID 33198372, 2020). "The prevalence of KRAS and BRAF mutations was found to vary significantly by tumor location, with mutations more prevalent among right‐sided metastatic colon cancers than left‐sided tumors." (PMID 31856410, 2020). "The majority was male (71%), nine (26%) had a right-sided tumor, and four (12%) had a BRAF mutation (all right-sided)." (PMID 31705176, 2020). "A systematic literature review and meta‐analysis were conducted to estimate the pooled prevalence of RAS and BRAF mutations by tumor sidedness in studies of mCRC patients." (PMID 31856410, 2020). "It should be noted that in the underlying trial and also in general there is a relevant association of BRAF-mutation with right-sided primary tumor localization affecting our overlapping findings." (PMID 32449003, 2020). "In particular, eight tumor samples reported a BRAF mutation of which 5 was p.Val600Glu, 1 p.Leu597Arg, 1 p.Val600Lys, and 1 p.Val600Asp all sufficiently covered (>200x) with an VAF > 19.0%." (PMID 33317587, 2020). "BRAF mutations have been shown to contribute to this effect due to distinct tumor‐intrinsic and microenvironment‐specific mechanisms." (PMID 32330348, 2020). "Whereas for OS, at the multivariate model, only tumor grade differentiation (HR = 5.26, 95% CI 1.98–14.01) and BRAF mutation status (3.71, 95% CI 1.07–12.89) were independent prognostic factors." (PMID 32872561, 2020). "The BRAF p.V600E mutations initially identified in the primary tumor biopsy were confirmed in ctDNA for 7/10 patients (70%)." (PMID 32486146, 2020).
tumor (continued). "BRAF-V600E-mutated tumours are also more common in the elderly but display an increased risk of recurrence; overlapping is seen to a great extent between MSI-high (MSI-H), BRAF-V600E mutations, right-sidedness, and high age." (PMID 32823998, 2020). "Mutations of RAS and BRAF occur early in colorectal carcinogenesis and “liquid biopsy” allows detection of mutated circulating tumor DNA (ctDNA)." (PMID 32517177, 2020). "In contrast, MSI-high, CIMP-high, BRAF mutation, and tumor-infiltrating lymphocytes (TIL) are characteristic in right-sided CRC." (PMID 33045001, 2020). "Inter- and intra-tumor heterogeneity always arises as a hazard in the treatment of BRAF-mutated CRCs." (PMID 33152998, 2020). "These alterations can occur in different genes considered “drivers” and can be mutually exclusive within the same tumor, such as BRAF and NRAS gene mutations." (PMID 32695793, 2020). "Our idea is that sEVs released by tumor cells with the BRAF mutation harbor messages to avoid such “oncogene antagonism” by targeting NRAS in the recipient cells, which potentially harbor NRAS mutations." (PMID 32575666, 2020). "For further detail analysis, the agreement of cfDNA and tumor DNA of BRAF V600Mx was 76%, KRAS Mx and NRAS Q61 mutations were 100%, NRAS G12/G13 mutations was 100%." (PMID 32284750, 2020). "The activation of the MAPK pathway through BRAF mutations leads to downstream production of several cytokines that promote tumor growth and immune evasion with autocrine or paracrine mechanisms." (PMID 32604720, 2020). "Amplification of MITF was found in BRAF/MEK inhibitor resistant tumours, which is probably associated with growth advantage when the MAPK pathway is inhibited." (PMID 32613561, 2020). "In pLGG, the prevalence of the BRAF p.V600E mutation varies notably depending on the histology and location of the tumor." (PMID 32164789, 2020). "Tumour samples obtained at the time of progression had confirmed BRAF splicing variants by transcriptome analysis." (PMID 33216826, 2020). "The number of metastatic sites, presence of BRAF mutation, right-sidedness of the primary tumor, platelets (log-transformed), and tdEVs (log-transformed) remained significant predictors of OS in the final multivariable model." (PMID 33333805, 2020). "Recent advances are moving toward the identification of pre-existing tumor features predictive of target agents’ efficacy, besides BRAF mutation, to better personalize treatment approach." (PMID 32054102, 2020). "CIMP-high MSI tumours are furthermore characterised by the frequent presence of mutations in the BRAF oncogene." (PMID 32647253, 2020). "In a study comparing KRAS and BRAF mutations in both metastatic CRC plasma cfDNA and tumour tissue, specificity and sensitivity of 100% for BRAF V600E mutation and 96% on KRAS point mutations have been demonstrated." (PMID 33144898, 2020). "VE1 antibody is a BRAF V600E-mutated protein-specific antibody; BRAF V600E positivity was defined as tumors with >5% of positively stained tumor cells, in accordance with our previous study." (PMID 32143442, 2020). "The BRAF mutation was more relevant with lymph node involvement, deeper infiltration of the bowel wall, mucinous, poorly-differentiated tumor with thrombus, and perineural invasion." (PMID 32161617, 2020). "BRAF inhibitors can reverse some of the immunosuppressive effects associated with the BRAF-mutant tumour microenvironment (discussed in Section 3), augmenting the immune response and turning them back into immunologically “hot” tumours." (PMID 32645969, 2020). "Expression of BRAF mutant protein causes the constitutive activation of the pathway which sustains tumor growth and is associated with poor clinical outcome." (PMID 31758407, 2020).